CXCL2 (C-X-C motif chemokine ligand 2)
Description:
Produced by activated monocytes and neutrophils and expressed at sites of inflammation. Hematoregulatory chemokine, which, in vitro, suppresses hematopoietic progenitor cell proliferation. GRO-beta(5-73) shows a highly enhanced hematopoietic activity.
Synonyms: GRO2; GROB; MIP2A; SCYB2; MIP-2a; MGSA-b; CINC-2a; MIP2
Tractability: Antibody: its Gene Ontology location is reachable by antibodies, with high confidence; UniProt places it where antibodies can reach, with medium confidence; UniProt predicts a signal peptide or a membrane-spanning region.
Target class: Secreted protein
Gene: Protein-coding gene on chromosome 4 (74,097,040 to 74,099,196, reverse strand). Ensembl gene ENSG00000081041.
Subcellular location: Secreted
Pathways (Reactome):
Signal Transduction: Chemokine receptors bind chemokines; G alpha (i) signalling events
Immune System: Interleukin-10 signaling
Gene Ontology:
Molecular function: protein binding; chemokine activity
Biological process: response to molecule of bacterial origin; chemotaxis; inflammatory response; cell chemotaxis; defense response; immune response
Cellular component: extracellular region
Genetic constraint (gnomAD): Loss-of-function variants: 12 observed, 12.03 expected, observed/expected ratio (o/e) 1, 90% interval 0.64 to 1.6. The upper end of that interval is the gene's LOEUF score, 1.6, which puts it in group 6 of 6, group 1 being the genes least tolerant of losing a copy. Missense variants: 120 observed, 124.48 expected, observed/expected ratio (o/e) 0.96, 90% interval 0.83 to 1.12. Synonymous variants: 68 observed, 52.19 expected, observed/expected ratio (o/e) 1.3, 90% interval 1.07 to 1.59.
Homologues: Orthologues: chimpanzee CXCL2 (92% identical). Paralogues in human: CXCL1 (90% identical), CXCL3 (88% identical), PPBP (47% identical), CXCL5 (44% identical), CXCL6 (38% identical), CXCL8 (38% identical), CXCL9 (37% identical), PF4 (35% identical), PF4V1 (32% identical), CXCL11 (25% identical), CXCL13 (25% identical), CXCL10 (24% identical).
Diseases named in the same sentence as CXCL2 in open-access papers:
CXCL2 is named in the same sentence as 355 diseases in open-access papers, as found by Europe PMC text mining. Sharing a sentence is not in itself a finding about the gene and the disease. The quoted sentences say what the papers report.
breast cancer (61 papers, 2013 to 2025). A primary or metastatic malignant neoplasm involving the breast. "In parallel, the expression of CXCL2 was closely related to the stage of breast cancer, with deficiency in stage X." (PMID 38021148, 2023). "Studies have also shown that knocking down CXCL1/CXCL2 by short hairpin RNA caused a reduction in metastasis from mammary tumors to the lungs." (PMID 36612163, 2022). "AKR1C3 and CXCL2 are ferroptosis-related genes associated with the immune microenvironment and prognosis in breast cancer." (PMID 36275721, 2022). "Recent studies revealed CXCL2 is also associated with acquired resistance in breast cancer, colorectal cancer and glioblastoma." (PMID 30871526, 2019). "For instance, trastuzumab-resistant HER2-positive breast cancer was found associated with downregulated TGFBI, CXCL2, and SLC38A1, which was silenced by DNA hypermethylation." (PMID 40464376, 2025). "Silencing CXCL1 and CXCL2 downregulates multiple metastasis-promoting genes and inhibits the metastatic potential of breast cancer cells." (PMID 41378129, 2025). "PMN-MDSCs are recruited to the mammary tumor by chemokines such as C-X-C motif chemokine ligand 2 (CXCL2)." (PMID 40165290, 2025). "Found in our data, CXCL2 is expressed at low levels in breast cancer cells and is positively correlated with the survival rate of patients." (PMID 38021148, 2023). "In particular, the upregulation of CXCL2 alone was sufficient to inhibit the proliferation activity and colony formation efficiency of MCF-7 cells, further indicating the critical role of CXCL2 in breast cancer." (PMID 38021148, 2023). "To illustrate the functional significance of CXCL2 during MCF-7 cell proliferation, accordingly, we found that CXCL2 was significantly downregulated in breast cancer tissues by the GEPIA database (P<0.05)." (PMID 38021148, 2023). "Bioinformatic analysis showed that CXCL2 was positively related to CCL20 in breast cancer patients (p value = 8.4e-31, R = 0.34), and CXCL2 was abundant and highly secreted by PMN-MDSCs in CCL20-overexpressing tumors." (PMID 36859354, 2023). "In a mouse model of breast cancer, tumor-associated mesenchymal stromal cells released CXCL1, CXCL2 and CXCL5, leading to increased neutrophil recruitment at primary tumor sites." (PMID 37566060, 2023). "Taken together, we demonstrated that chronic stress remodels lung pre-metastatic niche of breast cancer by enhancing expression of CXCL2 that recruits neutrophils into lung and by activating epithelial cells to produce ACh that promotes NETosis of neutrophils." (PMID 37773152, 2023). "Next, we explored the correlation between SHCBP1 and CXCL2 expression in breast cancer using the GEPIA database." (PMID 38021148, 2023). "Using a cytokine array, osteocyte-derived CXCL1 and CXCL2 cytokines were identified as regulators of migrating breast cancer cells." (PMID 37174109, 2023). "To reveal the signaling pathway involved in CXCL2-promoted breast cancer cell stemness, we treated 4T1 cells with rmCXCL2 or PBS and performed RNA-Seq analysis." (PMID 36859354, 2023). "Through inhibition of CXCL-1 and CXCL-2, curcumin diminished the formation of breast cancer lung metastases." (PMID 34948368, 2021). "Several differentially expressed mRNAs in HER2-positive breast cancer (including CXCL2, CXCL12, CXCL10, CXCL11, CXCL9 and CXCL14) were enriched in the biology processes of chemokine receptor binding and chemokine activity." (PMID 34257572, 2021). "CXCL2 was significantly expressed at high levels in 14 unique analyses and significantly expressed at low levels in 27 unique analyses in breast cancer." (PMID 34439306, 2021). "The Kaplan–Meier curves showed that in breast cancer patients, higher expression of mRNAs of CXCL2, 6, 9, 10, 12, 13, 14 and lower expression of mRNAs of CXCL3, 8, and 17 was significantly associated with longer overall survival (OS) (p < 0.05)." (PMID 34439306, 2021).
breast cancer (continued). "Curcumin monotherapy upregulated miR181b and downregulated miR181b targets, CXCL-1 and CXCL-2, in cells isolated from primary human breast cancers and MDA-MB-231 cells." (PMID 34948368, 2021). "In breast cancer, the groups with higher expression of mRNAs of CXCL2, 6, 9, 10, 12, 13, and 14 and the groups with lower expression of CXCL3, 8, and 17 had significantly better overall survival (OS)." (PMID 34439306, 2021). "Out of 12 CXCL chemokines, we found that the expression of CXCL8, CXCL1, and CXCL2 transcripts was significantly elevated in ER- breast cancer specimens compared to ER+ samples in seven, four and three independent studies, respectively." (PMID 33912188, 2021). "SEMA7A-silencing in a mouse model of mammary carcinomas induced the downregulation of pro-angiogenic proteins CXCL2/MIP-2, CXCL1, and MMP-9 in peritoneal elicited macrophages." (PMID 34209679, 2021). "Among them, breast cancer patients with high transcriptional levels of CXCL2/9/10/12/13 and low transcriptional level of CXCL3 were associated with a better prognosis." (PMID 32963527, 2020). "Our findings indicated that high CXCL2/9/10/12/13 expression and low CXCL3 expression were associated with favorable OS in breast cancer patients." (PMID 32963527, 2020). "SEMA7A can also promote angiogenesis in a hypoxia-independent manner in murine mammary carcinoma and in the cornea by stimulating macrophages to produce pro-angiogenic molecules, such as CXCL2/MIP-2 and VEGF-A." (PMID 30847405, 2019). "CXCL2, which regulates breast cancer metastasis and chemo-resistance, is also reduced by CDDO-Me treatment, implicating a potential role for CDDO-Me in the treatment of metastatic disease." (PMID 26918785, 2016). "Recently, it was shown that breast cancer cells expressing elevated levels of CXCL1 and CXCL2 induce the recruitment of MDSCs into the primary mammary tumor." (PMID 25882816, 2015). "Several chemokines that are known to recruit myeloid cells (CCL2, CCL9, CXCL2), including monocytes and neutrophils, were expressed by metastatic breast cancer cells." (PMID 25882816, 2015). "For example, SNAI1 transcribes CXCL1 and CXCL2 to regulate MDSCs infiltration in breast cancer." (PMID 41280721, 2025). "Furthermore, AQP3-mediated H2O2 transportation into cells was required to control Akt phosphorylation and consequent targeted cell migration of chemokine (C-X-C motif) ligand 2 (CXCL2)-dependent breast cancer cells in vitro." (PMID 38336645, 2024). "Besides, the suppression of CXCL2 in tumor cells impedes the invasive properties of osteosarcoma and breast cancer." (PMID 38637499, 2024). "Indeed, CXCL2 expression has been used to enhance the antitumor immunity of the oncolytic virus in orthotopic syngeneic murine breast cancer models through the enhancement of cytotoxic T lymphocytes." (PMID 38994929, 2024). "As expected, the SHCBP1 expression is negatively correlated with the expression of CXCL2 in breast cancer cell (P<0.01), suggesting that CXCL2 may play an important role in the proliferation of MCF-7 cells regulated by SHCBP1." (PMID 38021148, 2023). "Is CXCL2 involved in the regulation of breast cancer cell proliferation by SHCBP1?" (PMID 38021148, 2023). "In contrast to SHCBP1, breast cancer patients with low CXCL2 expression had poor overall survival." (PMID 38021148, 2023). "In addition, the gene-disease analysis showed that three out of four hub genes (CXCL2, SRC and SPP1) were also associated with mammary neoplasms, pulmonary fibrosis, dermatitis and allergic contact diseases." (PMID 35452485, 2022). "Additionally, the protein-disease interaction networks showed three out of five hub genes (CXCL2, SRC and SPP1) are also associated with mammary neoplasms, pulmonary fibrosis, dermatitis and allergic contact diseases." (PMID 35452485, 2022).
breast cancer (continued). "Interestingly, CXCL1 and CXCL2, including those produced by TAMs, were identified as capable of contributing to metastasis and chemoresistance in a mouse spontaneous breast cancer model." (PMID 33238581, 2020). "Neu+ mammary tumor line secreted G-csf, Ccl-1, Ccl-5, Cxcl-1, Cxcl-2, Cxcl-10, and Il-1ra." (PMID 31941005, 2020). "Furthermore, CXCR2 and several of its ligands (CXCL1, CXCL2, CXCL5, CXCL7 and CXCL8) have also been linked to breast cancer progression and metastatic invasion." (PMID 32581213, 2020). "Previous studies have demonstrated that CXCL2 plays an important role in anti-tumor drug resistance on various types of cancer, including breast cancer, colorectal cancer and glioblastoma, and modulates the property of migration, invasion and apoptosis in cancer cells." (PMID 30871526, 2019). "Similarly, CXCL1 and CXCL2 secretion by breast cancer cells resulted in increased infiltration of pro-tumorigenic myeloid cells and was further augmented by chemotherapeutic treatment, leading to chemoresistence." (PMID 30319622, 2018). "Moreover, AQP3-facilitated transport of H2O2 into cells was necessary to regulate protein kinase B (Akt) phosphorylation and subsequent directional cell migration of chemokine (C-X-C motif) ligand 2 (CXCL2)-dependent breast cancer cells in vitro." (PMID 28991174, 2017). "Considerably less is known about the functional roles played by CXCL2 in breast cancer metastasis." (PMID 25882816, 2015). "Therefore, what is the role of CXCL2 in breast cancer progression?" (PMID 38021148, 2023). "Therefore, what is the role of CXCL2 in breast cancer cells?" (PMID 38021148, 2023). "We noted elevated pro-inflammatory activity interactions, specifically with CXCL1, CXCL2, and CXCL8 in primary breast cancer." (PMID 40858590, 2025). "Similarly, some studies have found CXCL2 to have a pro-tumorigenic role in breast cancer, but others have found that it may promote anti-tumor immunity by potentiating responses to PD-1 blockade and increasing the infiltration of anti-tumorigenic N1 neutrophils in TNBC." (PMID 39623404, 2024). "In a combined cohort of breast cancer patients, c-Met expression is positively correlated to G-CSF, GM-CSF, CXCL1, and CXCL2." (PMID 37174093, 2023). "This article summarizes existing knowledge about the roles of CXCL ELR-positive chemokines CXCL1, CXCL2, CXCL3, CXCL5, CXCL6, CXCL7, and CXCL8 as peripheral blood and tissue markers in the diagnosis and prognosis of women with breast cancer." (PMID 37370728, 2023). "In this way, the expression of CXCL2/growth-regulated oncogene-β (GRO-β) and CXCL3/growth-regulated oncogene-γ (GRO-γ) also increases in breast cancer cells." (PMID 37108425, 2023). "Contrary to these studies, conditioned media from mechanically stimulated MLO-Y4 osteocyte-like cells increased breast cancer cell growth by producing CXCL1 and CXCL2." (PMID 37174109, 2023). "Spleen macrophages carrying breast cancer tumors secrete higher levels of proinflammatory mediators CCL2, CXCL2, MMP-9, and CHI3L1 stimulating this increased secretion." (PMID 38003338, 2023). "CCL20-modulated PMN-MDSCs secreted amounts of CXCL2 and activated NOTCH1/HEY1 signaling pathway in breast cancer cells by binding to CXCR2, leading to the increase of ALDH+ BCSCs." (PMID 36859354, 2023). "CXCL1, CXCL2, CXCL8, and CXCL12 were observed to diminish tumor response to chemotherapy, especially in breast cancers." (PMID 36612163, 2022). "Our RNA-seq results showed that the expression of CXCL1, CXCL2, CXCL3, and CXCL8 was significantly increased in breast cancer cells after co-culturing with adipocytes." (PMID 35280694, 2022). "The combination of CXCL2 plasmid DNA and HVJ-E treatment polarized neutrophils to N1 neutrophils, which activated CTL to suppress both primary and metastatic murine breast cancer legions." (PMID 33575480, 2021).
breast cancer (continued). "In another model of murine breast cancer, MMTV−Neu (Mouse Mammary Tumor Virus—Neu oncogene), we observed an increase of Cxcl1, Cxcl2, Cxcl3, and Cxcl5 levels in the tumor of MMTV−Neu animals compared to the mammary gland of WT animals." (PMID 34070438, 2021). "The results indicated that the expression levels of CXCL9, CXCL10, CXCL11, and CXCL13 were marked higher in breast cancer tissues than in normal tissues, while the expression levels of CXCL1, CXCL2, CXCL3, and CXCL12 were lower inversely." (PMID 32963527, 2020). "Previous studies have shown that CAFs production of CXCL1, CXCL2, PTGS2/COX-2, and IL-6 in breast cancer can modulate the functions of immune cells in TME." (PMID 26884644, 2016). "Given that SEMA7A is known to induce CXCL2/MIP-2, and PEMs from DA-3 mammary tumor bearers have increased CXCL2/MIP-2 and SEMA7A, we silenced the SEMA7A gene in DA-3 PEMs using shRNA." (PMID 24550834, 2014). "Similarly, CXCL2 activated the Notch1/Hey1 signalling pathway in breast cancer cells, leading to an increase in ALDH+ breast cancer stem cells." (PMID 39523215, 2024). "In addition to having angiogenic activity, CCL2, CXCL2, and MMP-9 can also act as chemokines to recruit tumor cells, myeloid-derived cells, and macrophages, providing conditions for breast cancer metastasis while promoting further deterioration of the tumor." (PMID 38003338, 2023). "However, the TCGA and Oncomine dataset showed that CXCL2 expression, alongside CXCR3 expression, is significantly lower in healthy tissues than in breast cancer (p < 0.001; p < 0.0001)." (PMID 37370728, 2023). "Indeed, the mRNA expression levels of CXCL2, TGFB1, CCL2, and IL1B were markedly increased in the breast cancer cell lines after treatment with Doxo and Abe." (PMID 37993606, 2023). "We speculated that the enrichment of ALDH+ BCSCs induced by CXCL2 might contribute to the increased CXCR2 expression, which provided a positive feedback loop to promote the stemness of breast cancer cells." (PMID 36859354, 2023). "Therefore, we believe that breast cancer cells express more CXCL1, CXCL2, CXCL3, and CXCL8 after co-culturing with adipocytes." (PMID 35280694, 2022). "The combination of CXCL2 DNA and HVJ-E (C/H) suppressed the growth of murine breast cancers in orthotopic syngeneic models by enhancing cytotoxic T lymphocytes and inhibited lung metastasis of breast cancer from primary lesions." (PMID 33575480, 2021). "There is a lack of articles discussing CCL2 and CXCL2 in the context of tumorigenesis of RCC; however, these chemokines were found to be associated with tumor growth and progression of melanoma and breast cancer." (PMID 28846693, 2017). "In addition, curcumin inhibits breast cancer metastasis by decreasing the inflammatory cytokines, chemokine (C-X-C motif) ligand 1 (CXCL1) and CXCL2." (PMID 27999817, 2016). "Our data showed overexpression of proinflammatory factors including CXCL1, CXCL2, CXCR4, CCL3, CCL4, IL-8, and PTGS2/COX-2 in the peripheral blood of patients with breast cancer both when considering the subtypes individually and when considering all breast cancer samples as a group." (PMID 26884644, 2016). "We also demonstrate that in vivo treatment with chitin microparticles, a substrate for CHI3L1, resulted in decreased production of CHI3L1, CCL2, CXCL2, and MMP-9 in BALF, and more specifically by interstitial and alveolar macrophages of mammary tumor-bearing mice." (PMID 24399973, 2013). "Furthermore, utilizing qRT-PCR, in vitro LDA, and AIG assay, we also confirmed that CXCL2 neutralizing antibody inhibited breast cancer cell stemness promoted by CCL20-modulated PMN-MDSCs, suggesting CCL20-modulated PMN-MDSCs promoted the cancer cell stemness by secreting amounts of CXCL2." (PMID 36859354, 2023). "In addition, CXCL2 was found to show significantly different expression in 5-FU responder and nonresponder breast cancer cell lines, suggesting its relationship with chemotherapy response." (PMID 23951052, 2013).
breast cancer (continued). "Moreover, we analyzed the expression of both SHCPB1 and CXCL2, and found that SHCPB1 is highly expressed in breast cancer cells or tissues from breast cancer patients compared to normal breast cells or adjacent normal tissues, while CXCL2 is lowly expressed in breast cancer cells or tissues." (PMID 38021148, 2023). "We have previously shown that splenic macrophages from mammary tumor-bearing mice secrete higher levels of the pro-angiogenic molecules CCL2, CXCL2, and MMP-9 (compared to non-tumor bearers) and that CHI3L1 stimulates this increased production." (PMID 24399973, 2013).